RIPK3 (receptor interacting serine/threonine kinase 3)
Diseases named in the same sentence as RIPK3 in open-access papers (continued):
Sharing a sentence is not in itself a finding about the gene and the disease.
tumor (continued). "RIPK3 has also been shown to modulate NKT cells function through a process independent of the necroptosis pathway, while promoting NKT cell-mediated anti-tumor immune responses." (PMID 38553639, 2024). "Necroptotic molecules, such as RIPK3 and MLKL, were already reported as prognostic markers in many tumor types." (PMID 37651429, 2023). "We then performed subcutaneous MOCK(TRAF6), MOCK(WT), MOCK(RIPK3−/−) and MOCK (MLKL−/−) group of cell transplantation tumor models through RIPK3−/− and MLKL−/− mice of C57BL/6 genetic background." (PMID 36604411, 2023). "CNV was positively correlated with the expression of NRGs except FASLG, RIPK3 and TNF in most tumours." (PMID 36583248, 2023). "Research has shown that necroptosis enhances CD8+ leukocyte-mediated anti-tumor immunity by activating RIPK1 and RIPK3 in the tumor microenvironment (TME)." (PMID 36836481, 2023). "Subsequently, we examined the relationship between the two core necroptosis-related genes, RIPK3 and MLKL, and tumor immune infiltration across different types of cancer." (PMID 37000317, 2023). "Surprisingly, in the majority of cancers, both RIPK3 and MLKL promoted tumor immune cell infiltration, particularly in BUC where MLKL increased the infiltration of neutrophils, which supports previous findings that necroptosis can boost antitumor immunity." (PMID 37000317, 2023). "Western blot analysis also showed that the protein expression levels of p-RIPK3 and p-MLKL in the tumor site were significantly upregulated after treatment with different doses of EBI in mice." (PMID 37397499, 2023). "It was found that the induction of necroptosis in endothelial cells promoted the extravasation and metastasis of tumor cells, and these effects were reduced by the RIPK1 inhibitor Nec-1 or specific knockdown of RIPK3 in endothelial cells." (PMID 37217473, 2023). "For example, knocking down RIPK1, RIPK3, and MLKL in colorectal and esophageal cancer cells inhibits tumor growth by reducing NF-κB activity." (PMID 36291937, 2022). "Other investigations have concluded that necroptosis/RIPK3 has a role in cancer mitigation and control; it has also been suggested that necroptosis-mediated inflammation and cell death may alternatively contribute to tumorigenesis and an immunosuppressive tumor microenvironment." (PMID 36224345, 2022). "To clarify the correlation between 7 PRGs (BTK, CASP5, EEF2K, GZMA, NR1H2, RIPK3, and SDHB) derived from LASSO Cox regression analysis and immune infiltration in COAD, we applied Tumor Immune Estimation Resource (TIMER) database on these genes." (PMID 35912258, 2022). "Accumulating evidence indicates that CRC tumours inhibit the process of necroptosis by regulating many regulators, such as RIPK1, RIPK3, and MLKL." (PMID 36139524, 2022). "The aurora kinase inhibitor CCT137690 triggers necroptosis in pancreatic cancer cells through RIPK1, RIPK3, and MLKL and thus suppresses tumor growth." (PMID 35662734, 2022). "Necroptosis is a novel form of programmed cell death distinct from apoptosis that enhances CD8+ T cell-mediated anti-tumor immunity via a mechanism involving RIPK3 and RIPK1 activation in the tumor microenvironment (TME)." (PMID 36291937, 2022). "Necroptosis is a form of programmed cell death regulated by three major mediators, RIPK1, RIPK3, and MLKL, is a key process in cancer biology, including tumor initiation and progression, invasion and migration, and tumor immunosuppression." (PMID 35965497, 2022). "Mechanistically, shikonin increases ROS production and upregulates the expression levels of RIPK1, RIPK3, and MLKL, which prompts necroptosis in apoptosis-resistant tumor cells." (PMID 36482419, 2022). "The differential analysis in normal breast tissue and tumor tissue revealed that, except for RIPK1, RIPK3, TNF, MAP3K7, and STAT3, all the other genes showed significantly differential expression in BRCA." (PMID 35686108, 2022).
tumor (continued). "CHMP2B, CHMP6, and RIPK3 were downregulated, while CXCL1, GPX4, and TRAF2 were upregulated in tumor samples." (PMID 36046241, 2022). "Other reports also describe higher RIPK3 and MLKL levels in human pancreatic cancer tissue, with MLKL expression even more intense at the tumor invasion front." (PMID 35422482, 2022). "Our results reveal a new necroptosis-mediated transcription circuit that is modulated by RIPK3 activation-dependent de-repression of TRIM28, which provides a mechanism to promote robust anti-tumor immunity and contributes to tumor immunogenicity." (PMID 34419074, 2021). "To determine the role of RIPK3 in human CRC, we analyzed the levels of RIPK3 expression in containing 41 normal intestinal specimens and 286 CRC tumor samples from the Cancer Genome Atlas (TCGA) transcriptome database." (PMID 33996591, 2021). "RIPK3 deletion in this PDA model or pharmacological inhibition of RIPK1 induce the recruitment of activated immune cells and favored tumor rejection." (PMID 34490126, 2021). "Of particular importance, RIPK3 was moderately expressed in both CCA and adjacent tumor tissues with a median H-score of 158.5 and 154.9, respectively." (PMID 34083572, 2021). "In this same cohort, tissue samples with high RIPK3 expression show strong reactivity to anti-CD8 and anti-Granzyme B antibodies, implicating the involvement of RIPK3 in regulating the anti-tumor microenvironment." (PMID 34419074, 2021). "Immunoreaction in tumor cells was detected in 30 cases (28%; range, 5%–80%) and in 17 cases (16%; range, 5%–50%) for AXL and RIPK3, respectively." (PMID 34745951, 2021). "RIPK3 immunoreactivity was differentially present and mainly localized in the cytoplasm of CCA tissues, normal cholangiocyte adjacent to tumor tissues, and cholangiocytes from normal liver tissues." (PMID 34083572, 2021). "Blocking IL-6 signaling suppressed tumor formation and reduced STAT3 activation in Apcmin/+Ripk3-/- mice." (PMID 33996591, 2021). "The expression of RIPK1, RIPK3, and MLKL, and the double ability of necroptosis of both promoting and reducing tumor development and growth, have been studied in a variety of tumors, in order to clarify the relationship with patient prognosis." (PMID 32326539, 2020). "In this study, moreover, patients with low tumor expression of RIPK1, RIPK3, and MLKL proved to have worse DFS." (PMID 32742497, 2020). "Early study highlighted the beneficial effects of RIPK3 and MLKL inhibitors on inflammation in animal models of disease ranging from ischemic injury to autoimmune disorders and neoplasia." (PMID 32854254, 2020). "The mRNA expression of RIPK1, RIPK3, and MLKL in tumor tissues was significantly correlated with each other (r = 0.46, P <0.001, between RIPK1 and RIPK3; r = 0.35, P <0.001, between RIPK1 and MLKL; r = 0.43, P <0.001, between RIPK3 and MLKL)." (PMID 32742497, 2020). "Furthermore, RIPK3 depletion reversed the effect of Beclin 1 depletion on tumour growth, which was induced by treatment with birinapant and emricasan, suggesting that depletion of Beclin 1 might be accelerating the necroptotic processes in the tumour model." (PMID 32457484, 2020). "We measured relative mRNA expression levels of RIPK1, RIPK3, and MLKL in tumor and corresponding normal lung tissues." (PMID 32742497, 2020). "Some other studies have reported that treatment with chemotherapeutic drugs induces the formation of the RIPK1/RIPK3/CASPASE-8 ripoptosome complex that triggers necroptotic cell death and that knockdown of RIPK3 can inhibit this killing of tumour cells." (PMID 32555451, 2020). "In SCCs, tumor tissues had significantly lower mRNA expression level of RIPK1 (P = 5 × 10-4), RIPK3 (P = 3 × 10-15), and MLKL (P = 1 × 10-5) compared to normal lung tissues." (PMID 32742497, 2020).
tumor (continued). "In this study, the authors found that CXCL1 is released from PDA cells in a RIPK3-dependent manner and CXCL1 blockage induces tumor regression by reducing the infiltration of immune suppressive MDSCs (myeloid-derived suppressor cells) and M2-like macrophages." (PMID 31922095, 2019). "Here we show that, contrary to expectation, necroptotic factors RIPK1, RIPK3, and MLKL promote tumor growth." (PMID 26959742, 2016). "In our study, we evaluated the effects of the necroptotic genes RIPK1, RIPK3, and MLKL in tumor growth and tumor resistance to therapy." (PMID 26959742, 2016). "Although there are some exceptions, both Ripk1 and Ripk3 mRNA expression was well correlated with their protein expression across different tumor lines (P=0.0168 for RIPK1 and P=0.002 for RIPK3 by Spearman correlation coefficients)." (PMID 25675296, 2015). "The anticancer effect was supposed to be the result of apoptosis induced by Peficitinib, according to immunostaining of the excised tumor, which was positive for cleaved caspase-3 and negative for RIPK3." (PMID 40883550, 2025). "Of note, the relative contribution of primary disease to global tumor burden as a determinant of ethical endpoint was not affected by the whole-body deletion of Ripk3 (p value: 0.1780) or Mlkl (p value: 0.2056)." (PMID 40494873, 2025). "Our findings in human tumor samples that MLKL and RIPK3 gene expression levels were upregulated during ICI treatment suggest a potential positive feedback loop by infiltrating immune cells which might further enhance necroptotic signaling in the TME." (PMID 40345706, 2025). "A therapeutic target may be to sensitize tumor cells with agents that induce PANoptosis through activation of ZBP1, CASP8, RIPK3, or other key components." (PMID 40422233, 2025). "Neither the Ripk3−/− nor the Mlkl−/− genotype significantly influenced tumor penetrance (data not shown), phenotype or latency (median TFS: 104 days and 83 days, respectively; p value: 0.9064 and 0.1875, respectively) in this setting." (PMID 40494873, 2025). "The expression and functional status of key molecules within the PANoptosome, such as ZBP1, RIPK1, RIPK3, CASP8, and ASC, may influence tumor viability and immune detection." (PMID 40422233, 2025). "Further assessment demonstrated that the expression of necroptosis-related genes, including FADD, MLKL, TLR2, PGAM, HMGB1, CXCL 1, TRAF2, and EZH2, was elevated in tumor tissue, while FAS, RIPK1, RIPK3, TLR3, TNFRSF, ALDH2, and NDRG2 were upregulated in normal intestinal tissues." (PMID 40959081, 2025). "It is not difficult to see that targeting RIPK1/RIPK3 in macrophages has the potential to be a potent target to restrain tumour progression." (PMID 38652105, 2024). "The median survival for the mice from both the RapaCas9 and HSV-TK groups was 15 days after rechallenge, whereas all mice from the group subjected to the RIPK3 system survived until the termination of the experiment, and no tumor growth was observed." (PMID 39560995, 2024). "RIPK3 has been reported to modulate the secretion of cytokines in the TME and thus mediate the innate and adaptive immune systems to regulate immune homeostasis and promote tumour progression." (PMID 38652105, 2024). "Elevated RIPK1/RIPK3 expression in necroptotic cells activated the NF‐κB‐dependent signals pathway, promoting CD8+ leukocyte‐mediated immune responses, and in combination with anti‐PD‐1 therapy, improved durable tumour clearance." (PMID 38594879, 2024). "RIPK1 and RIPK3 are mainly involved in controlling and executing necroptosis in keratinocytes, while RIPK4 controls proliferation and differentiation of keratinocytes and thereby can act as a tumor suppressor in skin." (PMID 37688617, 2023). "Tumor cells may undergo classic necroptotic events under hypoxic conditions by either inhibiting RIPK1 and RIPK3 expression or reprogramming glycolytic metabolism." (PMID 37169000, 2023).
tumor (continued). "Of note, previous studies have suggested that HSP90 can influence the activation and stability of crucial regulators involved in the necroptosis process, such asRIPK1, RIPK3 and MLKL, thereby contributing to immune cell recruitment and immunogenic cell death of tumor cells." (PMID 38149248, 2023). "Recent research has demonstrated that during tumor formation, tumor necroptosis might be induced by death factors to engage in the RIPK1 and RIPK3 pathways." (PMID 37274025, 2023). "In human tumor cells, the necroptosis pathway is often downregulated due to the absence of RIPK3 expression." (PMID 36768641, 2023). "RIPK1 and RIPK3 control and execute necroptosis in keratinocytes, as in other cell types, while RIPK4 controls proliferation and differentiation of keratinocytes and thereby can act as a tumor suppressor in skin." (PMID 37688617, 2023). "GEPIA database illustrated a downregulated RIPK3 in tumor tissue, but no significant change in Wanderer and UCLCAN database." (PMID 35907206, 2022). "Moreover, DMW also activated RIPK1, RIPK3, and MLKL axis in tumour tissues from xenograft mice, thus, suggesting a necroptotic effect." (PMID 35955595, 2022). "At the same time, it has been shown that tumor cells of astroglial origin (T98G, U251 and A172) efficiently evade necroptosis induced by chemotherapeutic agents because they do not express RIPK3 due to epigenetic modifications." (PMID 35898880, 2022). "RIPK3, a key kinase of necrotizing apoptosis, is significantly down-regulated in human colorectal cancer (CRC), and its expression has anti-inflammatory and anti-tumor effects in the intestine." (PMID 36357839, 2022). "Although it is generally accepted that necroptotic factors are anti-tumor factors, an astonishing result was discovered recently: that RIPK1, RIPK3, and MLKL may support tumor growth." (PMID 35884370, 2022). "Nevertheless, enhanced T-ALL development was observed only in Ripk3−/− mice and not in Mlkl−/− mice, suggesting that the tumor-repressive activity of Ripk3 is primarily independent of Mlkl-mediated HSC elimination." (PMID 35561683, 2022). "Activated RIPK3 could phosphorylate TRIM28 and increase the production of immunostimulatory cytokine in the tumor microenvironment, then emerge strong cytotoxic anti-tumor immunity." (PMID 36611858, 2022). "Given most of the tumor cells are independent of RIPK3 nor necroptosis, RIPK1 kinase activity has been shown to play a distinct role in tumor-associated macrophages (TAMs)." (PMID 39872161, 2022). "Our data suggest that RIPK3 activation-dependent derepression of TRIM28 in cancer cells leads to increased immunostimulatory cytokine production in the tumor microenvironment, which then contributes to robust cytotoxic anti-tumor immunity." (PMID 34419074, 2021). "The present study revealed both RIPK1/RIPK3/MLKL and RIPK1/caspase-8/caspase-3 pathways were inhibited in TNBC tumor samples and AQP1-expressing cell lines, which is in agreement with our presumption that both RIPK1-dependent necroptosis and apoptosis are attenuated by AQP1." (PMID 33980862, 2021). "On the other hand, some recent studies suggested that tumor necroptosis may be triggered by death factors and engages RIPK1 and RIPK3 pathway during tumor development." (PMID 33976222, 2021). "Notably, blocking IL-6 with a neutralizing IL-6 receptor antibody effectively attenuated tumor burden and STAT3 hyperactivation in Apcmin/+Ripk3-/- mice." (PMID 33996591, 2021). "Nevertheless, our work reveals ZBP1, not RIPK1, as the key mediator upstream of RIPK3 in tumor necroptosis and provide new insights about the regulation of tumor necroptosis during tumor development." (PMID 33976222, 2021).
tumor (continued). "The absence of RIPK3 exhibits dramatically increased tumor numbers in Apcmin/+ mice through the hyperactivation of IL-6/STAT3 signals." (PMID 33996591, 2021). "PGE2 leads to down-regulation of RIPK3, which in turn results in induction of COX-2 and increased production of PGE2 by the MDSCs, which in turn increases proliferation of cancer cells and inhibits the anti-tumor function of CD8+ T cells." (PMID 33364964, 2020). "Recent evidence suggests that standard chemotherapeutic drugs induce RIPK3-dependent necroptosis in multiple cancer cell lines and that chemotherapeutic drug-induced necroptosis rather than apoptosis reduces tumor growth in vivo." (PMID 31914150, 2020). "Remarkably, this loss of RIPK3 expression was gradually (rather than abruptly) achieved during tumor progression, both in patient tumor biopsies as well as xenograft tumor models, thereby suggesting a role for negative selection pressures against RIPK3." (PMID 32752206, 2020). "Notably, RIPK1, RIPK3 and/or MLKL are downregulated in various types of cancer, reflecting the necessity for tumor cells to circumvent necroptosis." (PMID 32366830, 2020). "The analysis of RIPK3 expression in CCA primary tissues by immunohistochemistry has been previously reported, but RIPK3 protein was expressed in most CCA tissues, with lower levels in tumor tissues than in the paired normal liver tissues." (PMID 31914150, 2020). "The mRNA expression levels of RIPK1 and RIPK3 were significantly lower in patients with tumor necrosis (P = 0.04 and P = 2 × 10-5, respectively) than in those without tumor necrosis." (PMID 32742497, 2020). "Although this study demonstrated the promoting effect of RIPK1 and RIPK3 in tumor development, necroptosis of tumor cells during tumor progression was not investigated." (PMID 31922095, 2019). "On the other hand, RIPK3 has been shown to be important for CD8+ T-cell cross-priming and antitumor immunity; therefore, inducing RIPK3 expression in tumor cells could increase their clearance by CD8+ T cells." (PMID 30157175, 2018). "This suggests the kinase activity of RIPK3 and therefore the ability for necroptosis to occur in the tumor microenvironment did not alter tumor nodule formation." (PMID 28151480, 2017). "Using bone marrow chimeras, the decrease in tumor nodules in the Ripk3−/− appeared to be due to the stromal compartment rather than the hematopoietic compartment." (PMID 28151480, 2017). "Although the number of B16-F10 cells increased by approximately 25% for a wild-type endothelial barrier, no increase in B16-F10 tumor cells was seen for a Ripk3−/− endothelial barrier." (PMID 28151480, 2017). "Loss of MLKL showed a reduction but not significant number of tumor nodules formed in the lung compared with Ripk3−/−." (PMID 28151480, 2017). "Taken together, our data show that RIPK3 positively regulates the activation of p38 and HSP27 upon permeability factor treatment (VEGF-A, VEGF-B, FGF-b) and therefore promoting permeability in the tumor cells to metastasize." (PMID 28151480, 2017). "Taken together, the data suggested that the reduction in tumor nodules in the Ripk3−/− mice was because of the stromal compartment and not because of the hematopoietic compartment." (PMID 28151480, 2017). "RIPK3 also displayed a lower level of expression in all clinical stages of CRC (stages I to IV) relative to healthy controls, implying a potential role for RIPK3 in tumor development." (PMID 27344176, 2016). "We also found an enhanced recruitment of inflammatory cells, including S100A9+ neutrophils, to the colons of Ripk3−/− mice after AOM-DSS, which is in line with the role of these cells in up-regulating the Wnt-β-catenin pathway in tumor cells and CRC progression." (PMID 27344176, 2016). "Cells from the 148I tumor also lacked any detectable RIPK3 expression and bore only low levels of MLKL." (PMID 27129149, 2016).